RAD51 (RAD51 recombinase)
Diseases named in the same sentence as RAD51 in open-access papers (continued):
Sharing a sentence is not in itself a finding about the gene and the disease.
glioblastoma (50 papers, 2013 to 2025). The most malignant astrocytic tumor (WHO grade IV). "In glioblastoma, Rad51 was overexpressed and negatively associated with overall survival." (PMID 35875146, 2022). "Similarly, we find that PTEN-deficient glioblastoma lines show pronounced RAD51 expression and form HR-responsive RAD51-positive and NHEJ-responsive 53BP1-positive DNA damage-induced foci." (PMID 33138032, 2020). "In addition, RAD51 protein expression in glioblastoma seems to be associated with poor progression-free survival." (PMID 27495836, 2016). "Furthermore, RAD51 holds the potential for involvement in the perpetuation of glioblastoma stem-like cells, entities speculated to underlie tumor growth, recurrence, and resistance to therapeutic regimens." (PMID 37887005, 2023). "With the inhibition of PRMT5, TMZ-induced RAD51 was subdued suggesting the role of PRMT5 in HR in the context of glioblastoma." (PMID 39989968, 2025). "The increase in Rad51 expression, as well as significantly inducing Rad51 foci formation in U251 and T98G glioblastoma cells after LCS1269 treatment, indicated the possible participation of the HR mechanism of reparation in DNA damage induced by LCS1269." (PMID 40649791, 2025). "Silencing of RAD51 has been shown to enhance glioblastoma sensitivity to TMZ, and augment the response to radiotherapy." (PMID 39989968, 2025). "In three human cancer cell lines—human epidermoid carcinoma (skin‐derived) A‐431, human glioblastoma U‐251 MG and human osteosarcoma U‐2OS—we observed that RAD51 subcellular localisation was primarily in the nucleoli, mitochondria and cytosol." (PMID 41350246, 2025). "Meanwhile, our data of GBM patients indicated that the RAD51 protein level was obviously elevated in glioblastoma tissues versus that in the peritumor tissues." (PMID 38049204, 2024). "At the molecular level, VPA leads to a downregulation of FANCD2 and RAD51, and the eradication of glioblastoma cells." (PMID 37763083, 2023). "RAD51 protein product is involved in DNA repair and is altered in 0.65% of all cancers with lung adenocarcinoma, glioblastoma and glioblastoma multiforme." (PMID 36845707, 2023). "Consistent with observations in glioblastoma tumors, RebL1 depletion suppressed DNA repair protein Rad51 in Tetrahymena, thus underscoring the evolutionarily conserved functions of RBBP4/7 proteins." (PMID 34086947, 2021). "The Bishop and Connell labs developed a small molecule RAD51 inhibitor, RI-1, that blocks RAD51 binding to ssDNA and radiosensitizes glioma and glioblastoma cells." (PMID 34337349, 2021). "The current study is the first demonstration that iPA enhanced at low concentration the radiosensitivity of glioblastoma cells by downregulating RAD51, a key player in HR repair, leading to impairment of a prompt DDR." (PMID 31993371, 2019). "Similar to U-2 OS (osteosarcoma), A-431 (epidermoid carcinoma), and U-251 MG (glioblastoma) cells Rad51 mainly resides in the nucleoli also in untreated H1339 control cells." (PMID 31569342, 2019). "Glioblastoma cell lines show an upregulation of HR genes, especially RAD51, BRCA1, and BRCA2, which leads to less DNA damage after irradiation." (PMID 31234336, 2019). "whereas, iPA pretreatment of glioblastoma cells reduced radiation induced RAD51 protein and mRNA levels and nuclear foci formation." (PMID 31993371, 2019). "This was previously observed in glioblastoma, where RAD51 expression decreases from CSC to progenitor cells." (PMID 31234336, 2019). "Due to the inhibition of RAD51, a delay of the G2 arrest led to a clear radiation sensitization in glioblastoma." (PMID 31234336, 2019). "RAD51 is a major component of HR-mediated DNA repair and is overexpressed in many cancers, including glioblastoma." (PMID 30282933, 2018). "Through targeting “HR-addicted” temozolomide-resistant glioblastoma cells via a chemical inhibitor of Rad51, we demonstrated that targeting HR is a promising strategy for glioblastoma therapy." (PMID 28852018, 2017).
glioblastoma (continued). "One of the key players of HR is Rad51, whose downregulation significantly sensitized glioblastoma cells to TMZ." (PMID 27626497, 2016). "RAD51 also contains FoxM1 binding sites in its promoter and its expression can be regulated in glioblastoma by this transcription factor." (PMID 24811120, 2014). "It has been demonstrated that B02 could reduce DNA DSB repair and lead to radio-sensitization in glioblastoma stem cells, indicating Rad51 as a crucial and selective DNA repair target for tumor stemness." (PMID 35875146, 2022). "In glioblastoma, increased CD9 expression was associated with maintenance of glioblastoma stem-like cells, while CD81 was associated with enhanced resistance to radiotherapy by promoting nuclear translocation of RAD51, a protein involved in detection and repair of DNA double strand breaks." (PMID 36203458, 2022). "Finally, we discovered HDR-suppressing functions of anticancer cardiac glycosides in human glioblastomas and glioma cancer stem-like cells via inhibition of DNA repair protein RAD51 homolog 1 (RAD51)." (PMID 32797168, 2020). "Because iPA may affect Jak2/Stat5 pathways involved in the transcription of RAD51 we next depleted STAT5a/b in glioblastoma cells by RNAi and tested the mRNA levels of RAD51." (PMID 31993371, 2019). "Overexpression of RAD51 in cancer has been widely documented, particularly in glioblastoma." (PMID 30282933, 2018). "Taking advantage of the “HR addiction” of TMZ-resistant glioblastoma cells, we also demonstrated that inhibition of Rad51, in combination with TMZ, might be a promising strategy for glioblastoma treatment." (PMID 28852018, 2017). "RAD51 inhibition could be a therapeutic strategy helping to treat a significant number of glioblastoma, in combination with radiotherapy." (PMID 27495836, 2016). "Besides, targeting FOXM1 also sensitized resistant glioblastoma cells to temozolomide by downregulating Rad51." (PMID 24824601, 2014). "Extending this finding from GBM patients with RT, we certificated the increased expression of RAD51 in glioblastoma tissues after RT treatment." (PMID 38049204, 2024). "This was further reinforced by a significant increase in the number of γH2AX-foci within the nucleus of glioblastoma cells, an indicator of DNA double-stranded breaks (p < 0.0001) and a concurrent reduction in the mean nuclear intensity of DNA-repair marker, RAD51 (p = 0.0002)." (PMID 38212807, 2024). "FOXM1 is a pro-oncogenic transcription factor that is overexpressed in glioblastoma multiforme (GBM) and correlated with increased RAD51 expression." (PMID 34208195, 2021). "Research into DNA repair pathways, particularly involving RAD51 and BRCA1/2, has shed light on their critical roles in glioblastoma." (PMID 37887005, 2023). "This is consistent with previous findings in which ATM inhibition profoundly decreased RAD51 foci formation, increased DNA damage or γH2AX foci formation, and impaired HRR through the downregulation of RAD51 in human glioblastoma, lung, and cervical carcinoma cells." (PMID 37020276, 2023). "In human glioblastoma (GBM) tumor cells, knockdown of RBBP4 causes sensitization of tumor cells to temozolomide (TMZ) chemotherapy and supresses the expression of several DNA repair genes, including RAD51, a key enzyme of the homologous recombination repair pathway." (PMID 34086947, 2021). "Furthermore, in glioblastoma cells, CHD4 was suggested to regulate RAD51 expression directly by binding to the RAD51 promoter and increase the acetylation of histone H3 at lysine 9 (H3K9Ac), possibly through an interaction with the CBP and p300 co-activators." (PMID 34208195, 2021). "Given that PLK1 inhibition resulted in an increased level of DNA damage in EGFRvIII expressing glioblastoma cells, we next tested whether the PLK1-mediated Rad51 phosphorylation played a significant role in glioblastomas." (PMID 26059434, 2015).
glioblastoma (continued). "In addition, HDACi reduce the expression of proteins involved in DNA repair (Rad51), mitotic spindle formation (TPX2) and chromosome segregation (Survivin) in glioma cells and in human glioblastoma multiforme primary cultures." (PMID 25275596, 2014). "High expression of MSI1, CHK2, and Rad51 and higher ATM phosphorylation was reported in radioresistant stem-like cells from patient-derived glioblastoma (GBM)." (PMID 34900673, 2021). "To determine whether expression of RAD51 or its paralogs is impacted by PTEN-dysfunction in primary tumors, we performed an RNA expression analysis amongst PTEN-mutant/deleted tumors derived from glioblastoma patients." (PMID 33138032, 2020). "In glioblastoma (GBM), pharmacological inhibition of FTO (e.g., using FB23-2) increases m6A modification on the target gene VEGFA, downregulating its expression and impairing DNA damage repair (e.g., sustaining γH2AX foci and reducing Rad51 recruitment)." (PMID 40823093, 2025). "RAD51 was negatively correlated with a majority of Immunol inhibitors, Immunol stimulators, and Chemokine receptors in esophageal carcinoma (ESCA) and glioblastoma multiforme (GBM)." (PMID 35359409, 2022). "Analysis of The Cancer Genome Atlas (TCGA) dataset of glioblastoma tissue specimens and the SKS dataset of patient-derived glioblastoma brain tumor initiating cells (BTICs) revealed no notable differential expression of RAD51 or its paralogs in PTEN-mutated or wild-type samples." (PMID 33138032, 2020).
glioma (46 papers, 2011 to 2026). A benign or malignant brain and spinal cord tumor that arises from glial cells (astrocytes, oligodendrocytes, ependymal cells). "DNA-PKcs deficient glioma cells are highly dependent on FEN1/BRCA1/RAD51 to survival and counteract replication stress." (PMID 35414100, 2022). "In the current study we have found that Homologous Recombination Repair deficiency in PTEN mutant glioma cells is further disabled after PARP inhibition due in part to RAD51 down-regulation." (PMID 25576921, 2015). "Notably, Onalespib has been found to effectively deplete key HR proteins, like CHK1 and RAD51, impairing HR repair and making patient-derived glioma stem cell lines more susceptible to radiation and TMZ." (PMID 39949745, 2025). "We observed associations of methylation of RAD51 in glioma, and of RAD51C and RAD50 in CLLE." (PMID 33676569, 2021). "Gliomas from SDHA GV carriers with less DSB accumulation showed a trend towards a higher mean nuclear IRS of RAD51 than those from ATM, BRCA2, and FANCA GV carriers with more DSBs." (PMID 41546701, 2026). "Previous studies have demonstrated that Onalespib significantly impairs DNA repair by depleting homologous recombination (HR) proteins such as CHK1 and RAD51, reducing HR repair and increasing glioma stem cell sensitivity to radiation and TMZ." (PMID 39949745, 2025). "And the expression pattern of RAD51 is inversely correlated with efficacy of radiotherapy or chemotherapy in glioma cells." (PMID 39865088, 2025). "A prognostic model of RAD51 for overall glioma was constructed as an example application of RAD51 as a biomarker." (PMID 35359409, 2022). "Elevated BRCA1 and RAD51 level were also observed in glioma patient samples compared with normal samples." (PMID 35414100, 2022). "RAD51 expression and the BRCA2 axis are new molecular targets for sensitizing glioma cells to alkylating anticancer drugs and are associated with DNA damage response (DDR)." (PMID 35884836, 2022). "Different from most of the previous pan-cancer studies, to further expand the clinical significance of this paper, a prognostic model of RAD51 for glioma was constructed as an example application of RAD51 for these cancer types." (PMID 35359409, 2022). "Results revealed that RAD51 expression, PRS type, Grade, Age, IDH mutation, 1p19q codeletion, and MGMTp methylation were significantly associated with the overall survival of glioma patients." (PMID 35359409, 2022). "Inhibition of FEN1 induces homologous recombination deficiency through impaired expression and assembly of BRCA1 and RAD51 in multiple glioma cell types and sensitizes these cells to the effects of DNA-PKcs deficiency." (PMID 35414100, 2022). "The nomogram demonstrated the practical and practicality and feasibility of the use of RAD51 for overall glioma prognosis." (PMID 35359409, 2022). "GSEA revealed significant enrichment of pathways including DNA replication, cell cycle, and homologous recombination with BRCA1 and RAD51 in the glioma samples." (PMID 35414100, 2022). "A reduction in Rad51 expression, for example, in glioma cells significantly increases radiosensitivity." (PMID 32355162, 2020). "Studies have also reported that FOXM1 promoted glioma resistance to TMZ chemotherapy via regulating DNA damage repair gene Rad51 and replication factor C5." (PMID 31796105, 2019). "Inactivation of the DSB repair gene NBN resulted in a sensitization to temozolomide in melanoma cells and the downregulation of RAD51 induced a temozolomide sensitizing effect in glioma cells." (PMID 27556305, 2016). "Further studies have demonstrated the involvement of RAD51 in resistance to IR in several established human glioma cell lines with RAD51 inhibition enhancing radiosensitivity of these cells." (PMID 27495836, 2016).
glioma (continued). "Our results show that the expression of Rad51, a protein involved in DNA repair by homologous recombination, is reduced in HDACi-treated glioma cells." (PMID 25275596, 2014). "Our study presents that BRCA1, BRCA2 and RAD51 are increased in the two glioma cell lines following treatment with TMZ." (PMID 25337721, 2014). "The data provides evidence that down-regulation of Rad51 or BRCA2 is a reasonable strategy for sensitizing glioma cells to killing by O6-alkylating anti-cancer drugs." (PMID 22073281, 2011). "For down-regulation of HR in glioma cells, we used an interference RNA (iRNA) approach targeting Rad51 and BRCA2, and for NHEJ we employed the DNA-PK inhibitor NU7026." (PMID 22073281, 2011). "It should be noted that the potency of berberine in downregulating RAD51 in ESCC cells is comparable to that of Gleevec in glioma cells." (PMID 21858113, 2011). "We demonstrated that IRT triple treatment of BT16 tumor cells with ONC201, TMZ and RT shows induction of ATF4 indicative of ISR activation, cleaved PARP as a marker of apoptosis, and suppression of RAD51, a selective DNA repair target to radiosensitize glioma stem cells in treated brain tumors." (PMID 40145650, 2025). "TMZ may also induce senescence and downregulation of mismatch repair proteins and the homologous recombination protein RAD51 in glioma cells." (PMID 40336841, 2025). "Western blots analysis was utilized to assess the apoptosis of treated cells and showed induction of ATF4 as marker of ISR activation, cleaved PARP as marker of cell death, and suppression of ATPase Rad51, a selective DNA repair target that radio-sensitizes glioma stem cells in brain tumor cells." (PMID 40145650, 2025). "This study had shown that RAD51 had strong prognostic power for overall glioma." (PMID 35359409, 2022). "Results showed that RAD51 expression, PRS type, Grade, Age, TMZ treatment, IDH mutation, and 1p19q codeletion were significantly and independently provided prediction confidence for overall survival of glioma." (PMID 35359409, 2022). "Similarly, decreases in RAD51 expression have been shown to reduce glioma cells capacity for DNA repair and increased glioma cells sensitization to radiotherapy." (PMID 35414100, 2022). "The upregulation of RAD51 reported in this study is also consistent with previously published in vitro studies showing increased expression of RAD51 mRNA and protein levels in glioma cell lines compared with normal human astrocytes in culture." (PMID 34771522, 2021). "Inhibition of RAD51 enhanced the radiation sensitivity of glioma stem cells." (PMID 34631528, 2021). "Based on our results above, we hypothesized that G0S2 enhances radiation resistance of gliomas through regulation of Rad51 or 53BP1." (PMID 30953555, 2019). "Previously published papers revealed that RAD51 was upregulated in response to IR in the first hours after irradiations in glioma cells and low dose gamma-irradiation induce RAD51 expression through increased oxidative stress, histone deacetylation and reduction of miR-193b-3p." (PMID 31336873, 2019). "This may be a result of loss of function in some aspects of DNA repair which is supported by slower repair of glioma cells and the persistence of high levels of Rad51 and DNA-PK in U87 cells throughout the cell cycle." (PMID 30469529, 2018). "Interestingly, HDACi also reduced the expression levels of Rad51 in glioma cell lines in comparison with untreated cells and TMZ-treated cells." (PMID 25275596, 2014). "In addition, BRCA1, BRCA2 and RAD51 are required for HR-dependent DNA repair pathway in TMZ-resistant glioma." (PMID 25337721, 2014). "The expression of O6-methylguanine-DNA methyltransferase (MGMT) abolished all these effects, indicating that O6-alkylguanine induced by these drugs is the primary lesion responsible for the formation of DSBs and increased sensitivity of glioma cells following knockdown of Rad51 and BRCA2." (PMID 22073281, 2011).